CYP2D6 (cytochrome P450 family 2 subfamily D member 6 (gene/pseudogene))
Diseases named in the same sentence as CYP2D6 in open-access papers (continued):
Sharing a sentence is not in itself a finding about the gene and the disease.
tumor (32 papers, 1996 to 2026). "We selected the rs3892097 variant in CYP2D6 because it is located in a genomic region frequently affected by LOH in various tumor types, leading to the exclusive retention of the LoF allele in a subset of patient tumors following LOH." (PMID 39368455, 2024). "It is mainly expressed in liver and lowered CYP2D6 activity and altered protein expression in the tumor microenvironment reduce the risk of TT genotype-associated HCC." (PMID 38649860, 2024). "We studied the association of CYP2D6 genotype and tamoxifen metabolites with tumor biomarkers and recurrence in a randomized phase III trial of low-dose tamoxifen." (PMID 33767162, 2021). "The TT genotype-associated decreased risk of HCC appears to be related to lowered CYP2D6 activity and altered protein expression in the tumor microenvironment, and ANGPTL6 is a promising new diagnostic and prognostic biomarker for HCC." (PMID 34412629, 2021). "So far, any association of treatment outcome to CYP2D6 genotype failed when using tumor tissue as DNA source." (PMID 35582146, 2019). "Thus, to address this problem, we performed label-free global proteome profiling with 34 normal livers and peritumors of 61 HCC patients to elucidate changes in the tumor microenvironment (TME) related to the CYP2D6*10 polymorphism." (PMID 34412629, 2021). "Thus, in relation to study design, different CYP2D6 polymorphisms are analyzed, and some studies use tumor tissue for genotype assessment, which can compromise the accurate characterization of the number and types of CYP2D6 alleles." (PMID 23346096, 2012). "Combination of the individuals with two CYP2D6 null alleles or with presumed reduced CYP2D6 activity due to concomitant use of an inhibitor defined an overall PM group, which showed a reduced time to tumor recurrence and reduced overall survival compared with all other individuals." (PMID 27713292, 2010). "The outcome was all-cause mortality, with predictors including age, race, menopausal status, tumour size, estrogen receptor status, radiation treatment, and CYP2D6 metabolizer status." (PMID 42100630, 2026). "In general, tumour organoids identified as CYP2D6 intermediate metabolizers were more sensitive to talazoparib than normal metabolizers, supporting its potential as therapy for heterozygous patients only retaining the LoF allele in their tumors." (PMID 39368455, 2024). "As reviewed recently, some inconsistencies in the role of CYP2D6 can be explained by the proportion of DNA isolated from peripheral blood cells or tumor tissue." (PMID 35582146, 2019). "In a multivariate Cox analysis including tumour stage, tumour size and lymph-node status, the result for CYP2D6 was less clear (P = 0.055)." (PMID 17244352, 2007). "However, a greater proportion of women with the CYP2D6*4/*4 genotype had node-positive disease relative to that of the entire group and once nodal status and tumor size were accounted for, only a trend to significance was evident." (PMID 27713292, 2010). "SHAP analysis revealed that white race, increased age, absence of radiation treatment, larger tumour size and the CYP2D6 poor metabolizer (PM/PM) genotype were associated with elevated mortality risk, whereas the extensive metabolizer (EM/EM) genotype was protective." (PMID 42100630, 2026). "In this study, we have identified a few commonly mutated genes in pre-NACT tumor samples from either sensitive (DNAH5, CYP2D6, NUTM1) or resistant (CSPG4, TUBA3D, SLC35G5) cases, which suggest that these genes could have a potential utility for prediction of the response to NACT." (PMID 35501919, 2022).
tumor (continued). "Moreover, those patients with the CYP2D6 polymorphic variants have more aggressive tumor, lower overall survival, and no response to tamoxifen treatment." (PMID 33369460, 2020). "The genes found to be down-regulated in tumor tissue were CYP3A4 in 56 patients (61%), CYP2C8 in 44 patients (48%), CYP2C19 in 30 patients (33%), CYP2D6 in 11 patients (12%), CYP3A5 in 7 patients (8%) and CYP1B1 in 2 patients (2%)." (PMID 29774122, 2018). "The GEP analysis showed that the down-regulated genes in tumor tissue were CYP3A4 in 56 patients (61%), CYP2C8 in 44 patients (48%), CYP2C19 in 30 patients (33%), CYP2D6 in 11 patients (12%), CYP3A5 in 7 patients (8%) and CYP1B1 in 2 patients (2%)." (PMID 29774122, 2018). "A key limitation is that genetic data were derived from formalin-fixed paraffin-embedded tumor tissue rather than blood, preventing us from fully assessing CYP2D6 metabolizer status, which is typically based on many polymorphisms." (PMID 40369345, 2025). "On a genetic level, a comparable study in a set of 20 paired samples of tumour and adjacent normal breast tissues from patients with infiltrating ductal carcinoma identified the expression of CYP1B1, CYP2B6, CYP2C, CYP2D6, CYP2E1, CYP4B1 and CYP11A1 in both tumour and control tissues." (PMID 33809117, 2021). "Studies related to other types of neoplasms or based on other isoenzymes from cytochrome P450, but not on CYP2D6, were excluded." (PMID 30536272, 2018).
infection (19 papers, 2011 to 2025). The state of being infected such as from the introduction of a foreign agent such as serum, vaccine, antigenic substance or organism. "Another novel AIH model is the CYP2D6 mouse model, which is generated by the infection of an adenovirus encoding for human CYP2D6, the best‐characterized autoantigen recognized by T cells and antibodies of AIH‐2 patients." (PMID 35263512, 2022). "Since CYP2D6 was proven to have homologous regions with Herpes virus and Cytomegalovirus genome, infection with such viruses could trigger loss of tolerance and autoimmunity." (PMID 35032321, 2022). "At later times after infection, the antibody reactivity spreads to other epitopes, which are predominantly located at the surface of the CYP2D6 molecule." (PMID 29503645, 2018). "A more comprehensive understanding of CYP2D6 variation will not only benefit successful P. vivax treatment, and eventual elimination, in Madagascar but all populations afflicted by this insidiously harmful infection." (PMID 35230160, 2022). "Importantly, even 8 weeks after infection, the highest titers of anti-CYP2D6 antibodies were determined for the initiating DPAQPPRD (aa263–270) epitope." (PMID 29503645, 2018). "However, the overall impact of CYP2D6 on infection dynamics is still not fully understood." (PMID 40827872, 2025). "In order to reduce the potential confounder effect of exposure to infection and adherence to PART, CYP2D6 profile within the ADF-R group was compared between sub-groups who experienced 1, 2 or more relapses." (PMID 30999967, 2019). "Both volunteers were screened to have CYP2D6 genotypes predicted to be extensive metabolizer phenotypes of primaquine, and as of ~3 years of long-term follow-up, no relapse of infection has been documented." (PMID 34609964, 2021). "Several studies have investigated the impact of infection on drugs of the nervous systems, mainly CYP2D6 substrates without always showing a significant impact." (PMID 34867341, 2021). "The expression levels of CPS1, CYP2D6 and CYP3A4 proteins were significantly lower in the 43d M(+) cell group compared to the 1d M(+) cell group, suggesting that the extent of CPS1, CYP2D6, and CYP3A4 inhibition was related to the length of infection." (PMID 29075618, 2017).
psychiatric disorder (19 papers, 2012 to 2025). A disorder characterized by behavioral and/or psychological abnormalities, often accompanied by physical symptoms. "CYP2D6 is involved in the metabolism of 5-HT in the brain, which is linked to psychiatric disorders, as well as the synthesis of serotonin and dopamine." (PMID 37581520, 2024). "Several CYP2D6 genetic polymorphisms are described to be associated with ultrarapid (UM) or poor drug metabolism (PM), inducing clinical resistance and/or adverse events, and might therefore be related to pharmacoresistant severe mental health disease." (PMID 29472872, 2018). "The present study involving patients with psychiatric disorders investigated the role of CYP1A2 and CYP2D6 genetic variants and patients’ CYP1A2 metabolic capacity influenced by non-genetic factors (e.g., sex, age, smoking behaviour) in olanzapine exposure." (PMID 37898643, 2023). "In this regard, CYP2D6 PM participants were more likely to have drug doses outside the regular range and more comorbidities related to nervous or psychiatric disorders, whilst UMs were less likely to have SUPDDR." (PMID 37513866, 2023). "The association of olanzapine plasma concentration normalized by the dose/bodyweight (C/D) with CYP1A2 and CYP2D6-status was investigated in patients with psychiatric disorders." (PMID 37898643, 2023). "5/9 patients with pharmacoresistant mental health disease presented functional CYP2D6 abnormalities." (PMID 35745668, 2022). "The polymorphic enzyme CYP2D6 plays a key role in the metabolism of around 25% of all clinically used drugs, among which many are used in treatment of psychiatric diseases." (PMID 33967790, 2021). "Five of the nine (55.6%) inpatients with pharmacoresistant mental health disease presented functional CYP2D6 abnormalities." (PMID 29472872, 2018). "More than half of our inpatient sample with pharmacoresistant mental health disease presented functional defects in CYP2D6 drug metabolism." (PMID 29472872, 2018). "Increased costs of $4,000 to $6,000 were found for patients with severe mental illnesses who have either poor or ultrarapid metabolism of the CYP2D6." (PMID 25587529, 2014). "Higher opioid consumption (>70 MME) showed a trend toward an increased risk of maternal PONV (adjusted RR = 2.56; 95%CI: 0.70–9.29; p = 0.36), after accounting for total opioid consumptions, CYP2D6 phenotype, average pain score over three postpartum days, age, race, BMI, and any mental illness." (PMID 41517024, 2025). "The present study focused on the impact of CYP1A2 and CYP2D6 genetic polymorphisms as well as CYP1A2 metabolizing capacity influenced by non-genetic factors (sex, age, smoking behaviour) on olanzapine blood concentration in patients with psychiatric disorders." (PMID 37898643, 2023). "Since many psychiatric drugs are metabolized by CYP2D6, development of such genotype-based dose algorithms may meet the expectations of personalized treatment of patients with psychiatric disorders." (PMID 33967790, 2021). "In addition, longer hospital stay durations were identified in patients with major depressive disorder categorized with a severe mental illness and who exhibit CYP2D6 poor metabolism." (PMID 25587529, 2014). "The present work focused on the impact of CYP1A2 and CYP2D6 genetic polymorphisms as well as of CYP1A2 metabolizing capacity influenced by non-genetic factors (sex, age, smoking) on olanzapine blood concentration in patients with psychiatric disorders (N = 139)." (PMID 37898643, 2023). "This may be linked to existing evidence of the involvement of specific polymorphisms of genes, such as CYP2D6, NAT2, and PON1, both in cellular detoxification and pathophysiology of psychiatric disorders and MCS, although further studies on these aspects are needed." (PMID 32916833, 2020).
psychiatric disorder (continued). "In this case report, we present PGx results for CYP2D6 genotyping in an inpatient sample of pediatric individuals hospitalized in CAP and presenting severe mental illness with repeated psychotropic treatment failure." (PMID 29472872, 2018). "CYP1A2 and CYP2D6 are important for the metabolism of psychoactive drugs, including SSRIs, and an increased hypersensitivity to these medications was described in ASD subjects compared to patients with other psychiatric disorders." (PMID 35663546, 2022). "Frequencies of PMs, IMs, and UMs were similar to those found in an Antillean population without psychiatric disease; Caucasian populations; and in patients using antipsychotic medication not metabolized by CYP2D6." (PMID 30131727, 2018). "In addition to the CYP1A2 and CYP2D6 variations, a multiple linear regression analysis was performed to estimate the influence of non-genetic factors, sex and age as well as of tobacco smoking, the CYP1A2 inducing factor on olanzapine exposure in patients with psychiatric disorders." (PMID 37898643, 2023).
cardiovascular disease (4 papers, 2012 to 2025). "The individualized use of metoprolol in elderly patients with cardiovascular diseases guided by the CYP2D6 genotype is necessary to increase the benefit of β-blockers and reduce drug-related adverse events." (PMID 35462926, 2022). "We designed a prospective, short-term clinical trial to investigate the impact of CYP2D6 genotypes on metoprolol tolerance and adverse events in 1036 Chinese Han patients with cardiovascular diseases." (PMID 35462926, 2022). "Further literature search indicates that CYP2D6 plays a very important role in cardiovascular disease." (PMID 22401035, 2012). "The latest consensus has changed CYP2D6 genotyping among Chinese population, while its impact on metoprolol tolerance and adverse events in elderly Chinese patients with cardiovascular diseases remains unclear." (PMID 35462926, 2022). "Considering this great impact as well as the limited evidence of the CYP2D6 phenotype in elderly patients, we designed a prospective cohort among elderly Chinese patients with cardiovascular diseases to investigate the impact of the CYP2D6 genotype on metoprolol tolerance and adverse events." (PMID 35462926, 2022). "This prospective, short-term clinical trial used the latest consensus on CYP2D6 genotype-to-phenotype translation in elderly Chinese Han patients with cardiovascular diseases and found that IMs have lower tolerance for metoprolol and higher incidence of metoprolol-related adverse events than NMs." (PMID 35462926, 2022).
myopathy (4 papers, 2014 to 2025). A disease of the muscle in which the muscle fibers do not function properly. "The association between CYP2D6 and atorvastatin-induced myopathy was significant in both discovery and validation cohorts, but since it is unclear whether CYP2D6 contributes to atorvastatin metabolism, mechanistic studies will be necessary before clinical translation could be considered." (PMID 25221728, 2014). "The currently available literature does not support genes other than SLCO1B1 and SIM clinical outcome, except for possibly CYP2D6 and atorvastatin-induced myopathy." (PMID 25221728, 2014). "CYP2D6*4 may be clinically relevant for atorvastatin-induced myopathy, but mechanistic studies are needed." (PMID 25221728, 2014).
infectious disease (3 papers, 2022 to 2025). A disorder directly resulting from the presence and activity of a microbial, viral, or parasitic agent in humans. "However, CYP2D6 currently has 51 EADGIs for medications used in behavioral health, cardiology, gastroenterology, oncology and hematology, infectious disease, neurology, reproductive and sexual health, and urology." (PMID 36556194, 2022).
genetic diseases (2 papers, 2006 to 2020). "Multidisciplinary research emerges as the best approach to incorporate additional concepts to refine and improve such functional/activity scores for the CYP2D6 gene, as well as for many other human genes associated with simple and complex genetic diseases." (PMID 33049937, 2020).
kidney diseases (2 papers, 2018 to 2023). "However, their PBPK model failed to predict atomoxetine disposition in 100% of East Asian populations with CYP2D6 EM or CYP2D6*10/*10 genotypes or phenotypes, drug interaction studies, and specific population with renal disease or hepatic impairment." (PMID 30120390, 2018).
brain disorder (1 paper, 2023). A disease affecting the brain or part of the brain. "More notably, CYP2D6 activity is associated with the incidence and prevalence of brain disorders." (PMID 36959176, 2023).
mouth (1 paper, 2025). "To assess whether genetic variations in CYP2D6 and CYP2C19 were associated with SAA and dry mouth, we compared genotype frequencies of those who had high SAA and dry mouth (n = 4) to those who had no high SAA and no dry mouth (n = 59)." (PMID 41347168, 2025).
movement disorder (1 paper, 2015). Neurological conditions resulting in abnormal voluntary or involuntary movement, which may impact the speed, fluency, quality and ease of movement. "Little research has been published on the association between risperidone induced movement disorders and CYP2D6 polymorphisms and contradictory findings are apparent." (PMID 26937359, 2015). "CYP2D6 genotype was analysed in a risperidone treated cohort selected on the basis of risperidone ADRs, specifically movement disorders and weight gain." (PMID 26937359, 2015). "This prompted us to evaluate the influence of CYP2D6 genetic variation in a cohort of South African patients who presented with marked movement disorders and/or weight gain while on risperidone treatment." (PMID 26937359, 2015). "CYP2D6 polymorphisms appeared not to associate with risperidone ADRs (movement disorders and weight gain) in this pilot cohort of risperidone-treated South African patients." (PMID 26937359, 2015). "Finally citalopram, listed as an inhibitor of CYP2D6, which was discounted previously due to lack of supporting documentation, did not appear in this study to increase movement disorders when co-prescribed with risperidone, although this should be investigated in a larger cohort." (PMID 26937359, 2015).
CYP2D6 also shares sentences with these, for which no sentence is quoted: dyslipidemia (4 papers); invasive breast carcinoma (4); hyperlipidemia (3); acute myeloid leukemia (2); Arrhythmia (2); asthenia (2); cardiac diseases (2); falciparum malaria (2); gastroesophageal reflux (2); Huntington disease (2); neurological diseases (2); panic attack (2); Parkinsonism (2); sexual dysfunction (2); acute intermittent porphyria (1); acute myocardial infarction (1); adenocarcinoma of the lung (1); agranulocytosis (1); allergic disease (1); Arthritis (1); astrocytoma (1); atrioventricular block (1); autism (1); Autoimmunity (1); behavioral disorders (1); brain cancer (1); cardiac hypertrophy (1); cardiomyopathy (1); cervical cancer (1); cervical intraepithelial neoplasia (1).
A further 78 diseases each share a sentence with CYP2D6 in 1 paper.